RNU6-496P (RNA, U6 small nuclear 496, pseudogene)
Gene: Small nuclear RNA gene on chromosome X (111,421,510 to 111,421,608, reverse strand). Ensembl gene ENSG00000251954.
Homologues: Orthologues: chimpanzee U6 (100% identical), macaque U6 (93% identical), dog U6 (73% identical), rabbit U6 (73% identical), mouse Gm25792 (71% identical), guinea pig U6 (61% identical), rat LOC120103222 (61% identical). Paralogues in human: RNU6-29P (78% identical), RNU6-1 (77% identical), RNU6-11P (77% identical), RNU6-16P (77% identical), RNU6-2 (77% identical), RNU6-25P (77% identical), RNU6-37P (77% identical), RNU6-38P (77% identical), RNU6-39P (77% identical), RNU6-3P (77% identical), RNU6-4P (77% identical), RNU6-5P (77% identical), and 1283 more.